WASF1 (WASP family member 1)
Description:
Downstream effector molecule involved in the transmission of signals from tyrosine kinase receptors and small GTPases to the actin cytoskeleton. Promotes formation of actin filaments. Part of the WAVE complex that regulates lamellipodia formation. The WAVE complex regulates actin filament reorganization via its interaction with the Arp2/3 complex (By similarity). As component of the WAVE1 complex, required for BDNF-NTRK2 endocytic trafficking and signaling from early endosomes (By similarity). Also involved in the regulation of mitochondrial dynamics.
Synonyms: KIAA0269; SCAR1; WAVE1; WAVE; WAVE-1; NEDALVS
Tractability: Small molecule: a structure with a bound ligand is known. PROTAC: ubiquitination databases record sites on it; its protein half-life has been measured.
Gene: Protein-coding gene on chromosome 6 (110,099,817 to 110,180,019, reverse strand). Ensembl gene ENSG00000112290.
Subcellular location: Cytoplasm, cytoskeleton; Synapse; Cell junction, focal adhesion
Pathways (Reactome):
Signal Transduction: RAC1 GTPase cycle; RAC3 GTPase cycle; RHO GTPases Activate WASPs and WAVEs; VEGFA-VEGFR2 Pathway
Disease: FCGR3A-mediated phagocytosis
Immune System: Regulation of actin dynamics for phagocytic cup formation
Gene Ontology:
Molecular function: protein binding; protein kinase A binding; small GTPase binding; Arp2/3 complex binding; protein kinase A regulatory subunit binding; actin binding
Biological process: actin cytoskeleton organization; lamellipodium morphogenesis; mitochondrion organization; positive regulation of Arp2/3 complex-mediated actin nucleation; Rac protein signal transduction; actin filament polymerization; cellular response to brain-derived neurotrophic factor stimulus; protein-containing complex assembly; receptor-mediated endocytosis; dendrite extension; dendritic transport of mitochondrion; modification of postsynaptic actin cytoskeleton; neuron projection development; positive regulation of neurotrophin TRK receptor signaling pathway
Cellular component: protein-containing complex; SCAR complex; actin cytoskeleton; cytoskeleton; cytosol; lamellipodium; synapse; cytoplasm; dendrite cytoplasm; focal adhesion; mitochondrial outer membrane; mitochondrion; postsynapse
Genetic constraint (gnomAD): Loss-of-function variants: 7 observed, 43.62 expected, observed/expected ratio (o/e) 0.16, 90% interval 0.09 to 0.3. The upper end of that interval is the gene's LOEUF score, 0.3, which puts it in group 1 of 6, group 1 being the genes least tolerant of losing a copy. Missense variants: 461 observed, 674.1 expected, observed/expected ratio (o/e) 0.68, 90% interval 0.63 to 0.74. Synonymous variants: 196 observed, 233.51 expected, observed/expected ratio (o/e) 0.84, 90% interval 0.75 to 0.94.
Homologues: Orthologues: chimpanzee WASF1 (100% identical), macaque WASF1 (99% identical), dog WASF1 (99% identical), guinea pig WASF1 (99% identical), mouse Wasf1 (98% identical), rat Wasf1 (97% identical), tropical clawed frog wasf1 (83% identical), zebrafish wasf1 (64% identical), rabbit WASF1 (63% identical), Drosophila melanogaster SCAR (36% identical), Caenorhabditis elegans wve-1 (28% identical). Paralogues in human: WASF2 (45% identical), WASF3 (44% identical).
Diseases named in the same sentence as WASF1 in open-access papers:
WASF1 is named in the same sentence as 48 diseases in open-access papers, as found by Europe PMC text mining. Sharing a sentence is not in itself a finding about the gene and the disease. The quoted sentences say what the papers report.
breast carcinoma (12 papers, 2009 to 2025). "The result demonstrated that WASF1 was only minimally expressed in HCC cell lines compared to that of breast cancer cell lines." (PMID 31068575, 2019). "Western blot analysis showed that WASF1 was barely expressed in HCC cell lines compared to that of breast cancer cell lines, which serve as positive controls." (PMID 31068575, 2019). "It has been extensively reported that the WASF1 complex is steadily expressed in breast cancer cell lines and is essential for the invasion of breast cancer." (PMID 31068575, 2019). "The involvement of some of the genes affecting cancer cell death–Adm, Cflar, Cyr61, Ddit4, Itgb1, Mapk1, Mapk8, Tgfβ2, Tpm1, Vegfα and Wasf1, was demonstrated in breast cancer cell lines." (PMID 19450255, 2009). "We found that compared to breast cancer cell lines, the expression of WASF1 was significantly lower in HCC cells, suggesting that WASF1 may not be involved in HCC malignancy." (PMID 31068575, 2019). "Six of the 11 non-mitosis related genes were previously associated with poor survival in breast cancer patients: KRT17, MMP12, SLC7A5, SQLE, GABRP and PA2G4, but the remaining 5 had not been previously associated with cancer risk: CCDC86, NUP107, NUTF2, WASF1 and ELOVL6." (PMID 23077491, 2012). "To verify our suspicion, we performed western blotting and qPCR to examine the expression of WASF1 in HCC cell lines and used breast cancer cell lines as positive control groups." (PMID 31068575, 2019). "In this analysis, SHOX2 expression levels were found to be significantly correlated with the expression of two WASF genes, WASF1 and WASF3, suggesting SHOX2 may promote breast cancer metastasis through WASF-mediated signaling." (PMID 34465361, 2021). "We have demonstrated previously that, unlike WASF3, WASF1 is not required for the invasion and metastasis of breast cancer cells." (PMID 34465361, 2021). "Therefore, we obtained two breast cancer cell lines, MCF-7 and MDA-MB-231, which were used as positive controls for examining WASF1 expression in HCC cell lines." (PMID 31068575, 2019). "The protein Wiskott–Aldrich syndrome protein family member 1 (WASF1), which interacts with Cytoplasmic FMR1-interacting protein 1 (CYFIP1), promoting tumour cell movement, invasion, and metabolism, is persistently expressed at high levels in highly invasive prostate and breast cancer cells." (PMID 40243822, 2025).
Intellectual disability (6 papers, 2019 to 2025). "Downstream of Rac1 in actin polymerization, mutations in PAKs and WASF1 can cause macrocephaly, seizures, intellectual disability, or ASD." (PMID 37255534, 2023). "In humans, de novo truncating variants in WASF1 (Wiskott–Aldrich syndrome protein family member 1) have been linked to presentations of moderate-to-profound intellectual disability (ID), autistic features, and epilepsy." (PMID 34356165, 2021). "Notably, a recent study has reported three nonsense WASF1 de novo mutations in five unrelated cases with Intellectual Disability and Seizures." (PMID 38572415, 2024). "Diseases associated with WASF1 include neurodevelopmental disorder with absence of speech and variable seizures and non-specific syndromic intellectual disability." (PMID 39596003, 2024). "The NEDD4L/RAC2/WASF1 may be a novel pathway associated with NEDD4L-related neurodevelopmental and intellectual disabilities." (PMID 39596003, 2024).
prostate carcinoma (6 papers, 2012 to 2023). A carcinoma that arises from epithelial cells of the prostate gland. "Many studies reported that the down-regulation of WASF1 could significantly inhibit the progression and invasion of prostate cancer and ovarian cancer and promote anti-drug-induced apoptosis of leukemia cells." (PMID 37393364, 2023). "Importantly, we observed that deletion of WASF1, the gene that codes for WAVE1, occurs more frequently with PTEN deletion in metastatic lethal vs. primary disease, suggesting that WASF1 loss represents an aggressive of subtype of prostate cancer." (PMID 25906751, 2015). "In addition, in prostate cancer, CKAP2, LASP1, BIRC5, WASF1, ASAP1 and RUNX2 mRNAs were recently identified as new miR-203 targets, suggesting that miR-203 could be a new prognostic marker and a therapeutic target in metastasis of prostate cancer." (PMID 23285092, 2012).
Cognitive impairment (3 papers, 2013 to 2021). Abnormal cognition is characterized by deficits in thinking, reasoning, or remembering. "We broadened the severity spectrum of WASF1-related NDD to include individuals with milder cognitive impairment without epilepsy." (PMID 34356165, 2021).
epilepsy (3 papers, 2021 to 2025). A brain disorder characterized by episodes of abnormally increased neuronal discharge resulting in transient episodes of sensory or motor neurological dysfunction, or psychic dysfunction. "The phenotypes of two independent patients, each carrying the p.Trp161Arg variant in WASF1 resulting from distinct genomic alterations—either c.481T > A95 or c.481T > C102—are similar, displaying ID, DD, epilepsy, and microcephaly." (PMID 39774290, 2025). "For example, we identified a de novo variant (c.215G>A/p.R72H, CADD score: 29.6) in WASF1 in an ASD subject who had epilepsy comorbidity from non-consanguineous parents." (PMID 38572415, 2024). "Intriguingly, this patient has no current evidence of seizures, including normal EEG, though larger numbers of individuals are needed to determine if the presence of epilepsy within WASF1-related NDD confers a higher likelihood of more severely affected cognitive outcomes." (PMID 34356165, 2021). "In sum, WASF1-related NDD can present as a broad phenotypic spectrum ranging from mild-to-profound GDD/ID with variable features of ASD, epilepsy, and motor impairment." (PMID 34356165, 2021).
cerebral palsy (1 paper, 2021). A group of disorders affecting the development of movement and posture, often accompanied by disturbances of sensation, perception, cognition, and behavior. "In fact, the diagnosis of cerebral palsy (CP) could be applied to several of the reported patients with WASF1-related NDD, particularly the hypotonic CP subtype." (PMID 34356165, 2021).
developmental delay (1 paper, 2021). "Recently, we identified the same variant of WASF1 in a Japanese patient with severe developmental delay, seizures, and distinctive facial features." (PMID 34845217, 2021). "A recurrent de novo pathogenic variant of WASF1, NM_003931:c.1516C>T [p.Arg506*], was identified in a 6-year-old female Japanese patient with severe developmental delay, hypotonia, hyperkinetic behavior, and distinctive facial features." (PMID 34845217, 2021).
endometriosis (1 paper, 2025). The growth of functional endometrial tissue in anatomic sites outside the uterine body. "Among its members, WASP family member 1 (WASF1) has been implicated in the progression of endometriosis." (PMID 40072086, 2025).
Salmonella Infections (1 paper, 2017). Infections with bacteria of the genus SALMONELLA. "The top one DCG identified is WASF1, which is an important gene in the Salmonella infection pathway and was not identified as a DEG (expression fold change: 1.08; t-test p value of 0.34)." (PMID 28529955, 2017).
cancer (34 papers, 2009 to 2025). A tumor composed of atypical neoplastic, often pleomorphic cells that invade other tissues. "Conceivably, SLPI seemingly accelerates the ability of cancer cells to migrate by upregulating genes associated with the organization of the actin cytoskeleton, including WASF1 and WASF3." (PMID 33016205, 2020). "Due to the actin cytoskeleton’s critical role in mediating cancer cell migration to the blood or lymphatic system, WASF1 has an essential role in cancer metastasis and invasion." (PMID 37393364, 2023). "NCKAP1 has been known to promote the malignancy of cancer cells by disrupting the structural stability of WAS protein family member 1 (WASF1) and is correlated with poor prognosis of patients in several cancer types." (PMID 31068575, 2019). "WASF1 has been shown to be a promoter of cell invasion in various cancer cell types, including prostate cancer, colorectal cancer, pancreatic cancer, and breast cancer." (PMID 31068575, 2019). "It should be noted, however, that while WASF1 and WASF2 are not essential to invadopodium formation, WASF2, in particular, has attracted significant attention for its potential as a prognostic indicator and role in the invasion of cancers, like melanoma, breast, and pancreatic cancers." (PMID 33467681, 2021).
tumor (21 papers, 2015 to 2025). "WASF1 and WASF2 belong to the WASF family and play an important role in cell invasion and migration, which are considered to be key steps in tumor metastasis." (PMID 37833936, 2023). "KU treatment downregulated the epithelial-mesenchymal markers Twist, Snail, and Slug and the metastasis-related genes CAPN1, CDC42, CFL1, IGF1, WASF1, and WASL in cells and tumor tissues." (PMID 30390003, 2018).
neurodevelopmental disorder (8 papers, 2018 to 2024). A behavioral and cognitive disorder with onset during the developmental period that involves impaired or aberrant development of intellectual, motor, or social functions. "In this study, the recurrence of the de novo variant in WASF1 was confirmed in association with severe neurodevelopmental disorders." (PMID 34845217, 2021). "In humans, defects in WASF1 have been associated with a neurodevelopmental disorder (NDD)." (PMID 34356165, 2021). "The initial report of five adult patients with WASF1 variants was the only previous report regarding variants of this gene; this is the second such report, reaffirming that rare but recurrent truncating variants of WASF1 are associated with severe neurodevelopmental disorders." (PMID 34845217, 2021). "Also, we have identified 15 de novo variants in genes that were previously implicated in ASD or related neurodevelopmental disorders (PHF21A, WASF1, TCF20, DEAF1, MED13, CREBBP, KDM6B,SMURF1, ADNP, CACNA1G, MYT1L, KIF13B, GRIA2, CHM, and KCNK9)." (PMID 38572415, 2024). "In conclusion, we detected the WASF1:c.1516 C > T (p.506*) in two Chinese girls by trio-WES, which confirmed that they suffered from Neurodevelopmental disorder with absent language and variable seizures ((NEDALVS, # 618707)." (PMID 37641121, 2023).
WASF1 also shares sentences with these, for which no sentence is quoted: infection (6 papers); melanoma (6); Anxiety (3); immunodeficiencies (3); pancreatic cancer (3); epileptic seizures (2); leukemia (2); Lowe Syndrome (2); Lynch syndrome (2); Nephropathy (2); schizophrenia (2); viral infection (2); Alzheimer disease (1); astrocytoma (1); autism (1); autism spectrum disorder (1); behavioral disorders (1); blood cancer (1); brain disorder (1); brain edema (1); breast tumors (1); diabetes (1); essential thrombocythemia (1); Exotropia (1); fragile X syndrome (1); glioblastoma (1); invasive breast carcinoma (1); lysosomal storage disorders (1); metastatic cancer (1); metastatic tumor (1).
A further 6 diseases each share a sentence with WASF1 in 1 paper.